UBFD1 (ubiquitin family domain containing 1)
Description:
May play a role as NF-kappa-B regulator.
Synonyms: UBPH; FLJ42145; FLJ38870
Tractability: PROTAC: ubiquitination databases record sites on it; its protein half-life has been measured.
Gene: Protein-coding gene on chromosome 16 (23,557,721 to 23,574,394, forward strand). Ensembl gene ENSG00000103353.
Subcellular location (Human Protein Atlas): Nucleoplasm; Midbody; Nucleoli
Gene Ontology:
Molecular function: cadherin binding; RNA binding
Genetic constraint (gnomAD): Loss-of-function variants: 12 observed, 32.79 expected, observed/expected ratio (o/e) 0.37, 90% interval 0.23 to 0.59. The upper end of that interval is the gene's LOEUF score, 0.59, which puts it in group 2 of 6, group 1 being the genes least tolerant of losing a copy. Missense variants: 337 observed, 391.21 expected, observed/expected ratio (o/e) 0.86, 90% interval 0.79 to 0.94. Synonymous variants: 178 observed, 161.15 expected, observed/expected ratio (o/e) 1.1, 90% interval 0.98 to 1.25.
Homologues: Orthologues: chimpanzee UBFD1 (99% identical), macaque UBFD1 (99% identical), dog UBFD1 (99% identical), pig UBFD1 (97% identical), mouse Ubfd1 (97% identical), guinea pig UBFD1 (95% identical), rabbit UBFD1 (89% identical), rat Ubfd1 (79% identical), zebrafish ubfd1 (68% identical), tropical clawed frog ubfd1 (66% identical).